CDK6 (cyclin dependent kinase 6)
Diseases named in the same sentence as CDK6 in open-access papers (continued):
Sharing a sentence is not in itself a finding about the gene and the disease.
cancer (continued). "Additionally, it was proposed that palbociclib, an inhibitor of cyclin dependent kinase 6 (CDK6), could serve as an alternative therapeutic choice for targeting cancers with SRSF2 mutations." (PMID 39034387, 2024). "Thus, we report Selonsertib as a CDK6 inhibitor for the first time, which may be implicated in cancer control and prevention." (PMID 35720007, 2022). "Based on these results, we hypothesized that CDK6 was associated with cancer progression from the NMIBC to MIBC stage and approximately one-fourth of BLCA cases (23% in TCGA database and 29% in GSE13507 cohort), displayed high CDK6 transcriptional levels correlated with reduced survival." (PMID 35463324, 2022). "Given that cyclin D1 is the most widely expressed cyclin D in different cell types and is most frequently implicated as a cancer driver in solid tumors, we hypothesize that, in many clinical settings, activation of CDK6 may be enhanced by the assembly function of p21CIP1 or p27KIP1." (PMID 29091774, 2017). "In addition to PIM1, miR-33a has been also shown to directly target a variety of genes associated with cancer progression including several genes associated with cell cycle regulation such as CDK6 (cyclin-dependent kinase 6) and CCND1 (cyclin D1), which are directly targeted by miR-33a." (PMID 28947967, 2017). "Palbociclib (CKI) is a selective inhibitor of cyclin-dependent kinases CDK4 and CDK6, which blocks cell cycle progression at the G1/S transition and effectively suppresses cancer cell proliferation." (PMID 41362743, 2026). "Missense mutations of specific p16INK4a residues that are directly involved in the interaction with the N-lobe of CDK6, such as D74 and D84, have been frequently found in cancers." (PMID 39898030, 2025). "Despite CDK6's established oncogenic potential and therapeutic relevance across cancer types, its regulatory mechanisms and specific contributions to EC progression remain poorly understood, necessitating further investigation." (PMID 41287970, 2025). "CDK6 has received considerable attention over the past years as a major driver of cancer, including hematopoietic malignancies." (PMID 39898030, 2025). "Among the CDKs, cyclin-dependent kinase 6 (CDK6) is frequently found to be overexpressed in multiple types of human cancers and plays a pivotal role in regulating cell cycle progression." (PMID 40076203, 2025). "Cyclin-dependent kinase 6 (CDK6) has been identified as a potential drug target in various types of cancers." (PMID 40076203, 2025). "In cancer cells, CDK6 overexpression often outcompetes CDK4 in driving cell cycle progression, contributing to resistance against CDK4/6 inhibitors (CDK4/6i)." (PMID 40093074, 2025). "Our findings bridge the gap between the structural similarity and functional divergence of CDK4 and CDK6, advancing the understanding of kinase regulation in cancer biology." (PMID 40093074, 2025). "ELF4 can complex with TRIB3 to promote CDK6 expression, which is involved in EC cell proliferation and cancer stemness activities." (PMID 41287970, 2025). "Targeting CDK6 in cancer represents an attractive therapeutic option as CDK6 activity is frequently enhanced in disease and CDK4/6 kinase inhibitors are available for clinical use." (PMID 39966356, 2025). "Cyclin-dependent kinases CDK4 and CDK6 (CDK4/6) are effective targets in cancer therapy since their overexpression and dysregulation are implicated in a wide range of human cancers." (PMID 40696167, 2025). "Elevated CDK6 expression has emerged as a prognostic biomarker and predictor of chemosensitivity in various cancers, including EC." (PMID 41287970, 2025). "This study highlights the therapeutic potential of T. siliquosa root extract as a natural and multi-compound agent capable of targeting cyclin-dependent kinases CDK4 and CDK6, which are key drivers of cell cycle progression in various cancers." (PMID 40722732, 2025).
cancer (continued). "CDK4 and CDK6 are key proteins of cellular entry into the S phase, which is critical for the onset and progression of many cancers." (PMID 40138292, 2025). "Experimental results indicate that high doses of DEH can also suppress the expression of CDK4, CDK6, and p21, regulating the cell cycle, inducing cell cycle arrest in cancer cells, and promoting apoptosis in cancer cells." (PMID 40468178, 2025). "Compound 35 showed high binding affinity to Cyclin-Dependent Kinase 6 (CDK6), downregulated its protein expression at the translational level and inhibited cell growth in different human cancer cells lines." (PMID 40941984, 2025). "The greatest success has come from inhibiting cell cycle CDKs, especially CDK4 and CDK6, in certain cancer types." (PMID 39800748, 2025). "Our results confirmed previous findings in other cancer cell types that CDK6 is a target of miR-449a." (PMID 40495204, 2025). "In human cancers the roles of CDK6 extend beyond cell cycle regulation, involving transcriptional regulation and interaction with various proteins." (PMID 39800748, 2025). "These medications target CDK4 and CDK6 proteins on cancer cells, inhibiting cellular proliferation and blocking the progression from G1 to S phase in the cell cycle." (PMID 40136358, 2025). "Upregulation and activation of NF-κB contribute to unregulated cell proliferation in cancer cells, given that NF-κB transcription factors regulate the expression of cell cycle regulators such as cyclin A, cyclin D1, or cyclin-dependent kinase 6 (CDK6)." (PMID 38727313, 2024). "Increased CDK6 protein expression can be detected in many types of cancer, and reducing CDK6 expression inhibits the growth and proliferation of tumors in vivo and in vitro." (PMID 38711992, 2024). "Among these, cyclin-dependent kinases 4 (CDK4) and 6 (CDK6) are pivotal in mediating the transition of cells into the S phase, essential for the initiation, growth, and maintenance of numerous cancer types." (PMID 39004679, 2024). "Studies showed that human epidermal growth factor receptor (HER), SHP-2, mammalian target of rapamycin (mTOR), and cyclin-dependent kinase 4/cyclin-dependent kinase 6 (CDK4/CDK6) inhibitors improved adagrasib efficacy in KRAS G12C-mutant cancers." (PMID 38397927, 2024). "Ccnd1 triggers the G1–S phase transition in the cell cycle by activating cyclin-dependent kinases (Cdk4 and Cdk6) and enhances the proliferation of cancer cells." (PMID 38251008, 2024). "CDK6 mediates the cellular transition to the S phase and has a vital function in the onset, development, and persistence of various forms of cancer." (PMID 38633613, 2024). "Among this series, St.26 and St.27 showed significant activities against a panel of cancer cell lines and CDK6 enzymes." (PMID 39404419, 2024). "It targets cancer-causing genes such as BCL2, MCL1, and CDK6, and its reduction leads to increased cell growth and resistance to cell death." (PMID 39061157, 2024). "As the fundamental driver of the cell cycle from G1 phase to S phase, CDK6 plays an important role in the progression of cancer." (PMID 38212482, 2024). "Cyclin D1 is an important cell cycle regulatory protein responsible for activating CDK4 and CDK6 kinase activities and promoting cancer cell proliferation." (PMID 39768127, 2024). "All ATRT cell lines depend either on CDK4 or CDK6 expression in a mutually exclusive manner, a pattern recapitulated by most human cancer cell lines, and most require expression of at least one out of three D-type cyclins." (PMID 39617889, 2024). "WB detected protein expression levels of CDK4, CDK6 and cyclin D1, which were key cell cycle proteins for cancer proliferation." (PMID 38195969, 2024).
cancer (continued). "Decreased expression of CDK6/Reduce the viability and colony-forming potential of cancer cells/Decreased ROS production and CDK6 expression to induce apoptosis." (PMID 39712006, 2024). "In summary, a deepened understanding of the metabolic roles of CDK4/6 will open up avenues for the diagnosis of and metabolic interventions against KSHV malignancies and cancers with dysregulated Cyclin D/CDK4/CDK6 activities." (PMID 38365882, 2024). "ATP‐competitive CDK6 inhibitors (CDK6i) such as palbociclib, ribociclib, or amebaciclib have been studied for the treatment of various types of cancers." (PMID 38845697, 2024). "CDK6 plays a key role in the regulation of the cell cycle and is considered a crucial target for cancer therapy." (PMID 38893554, 2024). "First, we performed pan‐cancer analysis of CDK6 with TCGA and GTEx databases, and then further validated CDK6 expression using the GEPIA." (PMID 36457244, 2023). "As expected, the levels of γH2AX and cytoplasmic dsDNA were found increased in Cdk4−/− and Cdk6−/− cancer cells." (PMID 37833461, 2023). "We show that CCNI activates CDK6 to increase cancer cell proliferation via pRb phosphorylation, suggesting that CCNI is another piece in the cell cycle machinery puzzle and a new potential oncogenic driver." (PMID 37081792, 2023). "Based on importance in promoting cancer initiation as well as progression, CDK2 and CDK6 have drawn intense interest as promising therapeutic targets for cancer." (PMID 36342274, 2023). "Emerging evidence manifests that cyclin‐dependent kinase 6 (CDK6) plays an essential part in the initiation and progression of several types of human cancer, and its descending expression is correlated with an adverse prognosis." (PMID 36457244, 2023). "Among them, we selected Il-21, Cxcl13, Cdk6, Cdk1, and Cxcr7, all cytokine, cell cycle, or cancer-related genes." (PMID 37304286, 2023). "Among the various CDK targets from the CDK family, CDK-6 has emerged as a promising target as it is expressed in most common cancers and has a crucial role in driving cell cycle entry and cell progression." (PMID 38019988, 2023). "For instance, palbociclib, an inhibitor of the cyclin-dependent kinases CDK4 and CDK6 used in HR+/HER2- cancer treatment, has been observed to directly bind to and inhibit STING." (PMID 38139802, 2023). "The findings from the current study support the notion that the tested compounds are effective CDK-6 inhibitors for cancer treatment." (PMID 38019988, 2023). "In an in-silico study conducted on dietary phytoconstituents utilizing CDK6 as target proteins, ellagic acid was reported as potent CDK6 inhibitor inducing apoptosis of cancer cells." (PMID 37925393, 2023). "miR-125 regulates the proliferation of cancer cells through the inhibition of the expression of cell cycle regulatory proteins, CDK6 and Cyclin A2." (PMID 37958720, 2023). "Cdk6−/− cancer cells grew up to 100mm2 in Ifnar1−/− mice, though still smaller than control group, were still larger than those in WT C57 mice." (PMID 37833461, 2023). "CDK6 is a recognized cell cycle kinase facilitating cancer cell proliferation to promote cancer progression." (PMID 36755807, 2023). "In this research, we first analyzed the expression of CDK6 in pan‐cancer and explored its relationship with prognosis." (PMID 36457244, 2023). "Minichromosome maintenance complex component 7 (MCM7) and cyclin dependent kinase 6 (CDK6) are classical cancer-related genes that are essential for genome replication and regulating the cell cycle, respectively." (PMID 37005685, 2023). "First, the expression of CDK6 in normal and cancer tissues were examined by integrating TCGA and GTEx datasets." (PMID 36457244, 2023). "The downregulation of the PI3K/AKT pathway by fucoidan contributed, in part, to a reduced expression of CDK-4, CDK-6, cyclin-E, and cyclin-D1, consequently halting cancer cell growth while inducing the apoptosis of the cancer cells." (PMID 38248653, 2023).
cancer (continued). "CXCR2 activation also reduces the expression of p21 and increases the expression of cyclins and cyclin dependent kinases such as cyclin A, cyclin B1, cyclin D1, cyclin E, CDK2, and CDK6, thereby promoting the increased proliferation of cancer cells." (PMID 37686093, 2023). "Among the existing strategies in cancer therapy, targeting cyclin-dependent kinases (CDKs), especially CDK-6 is found to be one of the most promising targets, as this enzyme plays a pivotal role in cell cycle stages and cell proliferation." (PMID 38019988, 2023). "In SHH, we identified DMPs in four genes (CDK6, COL25A1, MMP16, PRIM2) that encode proteins which are the target of therapies in clinical trials for other cancers." (PMID 37035203, 2023). "Specifically, CDK6 regulates the progression of the cell cycle from the G1 to the S phase, and its expression is often increased in a variety of cancers." (PMID 36979715, 2023). "Taurine has an inhibitory concentration 50 (IC50) value equal to 4.44 μM and, according to an enzyme-inhibition assay, is considered a good inhibitor to treat cancers directed by CDK6." (PMID 37834106, 2023). "CCND1 is a downstream effector in the Wnt2/β-catenin pathway and activates the cyclin-dependent kinases (CDKs) CDK4 and CDK6 to promote cancer proliferation." (PMID 37056769, 2023). "As we have demonstrated that the use of LRPPRC-specific inhibitor, GAA, reduces CDK6 expression, we offer a approach for therapy against cancer stem cells by targeting LRPPRC." (PMID 37452037, 2023). "On the contrary, some core kinases and transcription factors involved in cancer such as CDK6, ERBB2, JAK1, DAPK1, FOXO1, and RXRA were highly expressed in S-III." (PMID 38143770, 2023). "CDK6 is important for cancer progression and is responsible for the regulation of key metabolic processes and cell cycle progression." (PMID 38107139, 2023). "Multiple studies demonstrated the importance of Cyclin-dependent kinase 6 (CDK6) for cell cycle progression in cancer cells, placing this gene in the oncogene category." (PMID 37624039, 2023). "Pharmacologic inhibitors of CDK4/CDK6 result in G1 phase cell cycle arrest, suppressing cancer cell proliferation." (PMID 35789211, 2023). "miR-124 and miR-137 molecules regulate the expression of the CDK6 gene and contribute to lowering the level of the CDK6 protein, which is involved in the development of a number of malignant tumors." (PMID 36834933, 2023). "Over the past decade, cyclin‐dependent kinase 6 (CDK6) has received increasing attention as a target for cancer therapy." (PMID 36457244, 2023). "In this work, through using CRISPR activation and shRNA knockdown approaches, we find that CDK6 is critically involved in the regulation of cancer stemness and has clinical significance." (PMID 37872167, 2023). "It facilitates G1 to S cell cycle transition and certain cancer cells require CDK6 for proliferation." (PMID 37298284, 2023). "CDK6 is a critical mediator in the cellular transition into the S phase, and its overexpression plays an important role in driving tumorigenesis in many cancer types." (PMID 37744274, 2023). "Cyclin-dependent kinases (CDKs) such as CDK4/CDK6 overexpression are common in different cancers including TNBC." (PMID 37190133, 2023). "CDK6, which supports the growth and viability of various cancer cells, was hampered by the dose-dependent manner of quercetin (IC50 dose of QR for A-549 cells is 52.35 ± 2.44 μM)." (PMID 36926328, 2023). "Based on pathological cyclin D1-associated kinase activity, such as in cancer, CDK4/CDK6 expression can be deranged, overexpressed, or altered." (PMID 37190133, 2023). "Consistent with our findings, CDK6 overexpression in PLC/PRF/5 cells significantly enhanced tumorigenicity with an increase in the estimated cancer stem cell (CSC) frequency." (PMID 37872167, 2023). "As a use case of DepLink, we further investigated CDK6, as it is one of the most promising targets of cell cycle-based cancer therapy." (PMID 37359725, 2023).
cancer (continued). "Our study aims to investigate the protective effect of a probiotic agent, S. boulardii, which can be effective in diarrhea associated with malignancy treatment, CDK4 and CDK6 inhibitors are used in this study." (PMID 36945921, 2023). "Fluorescence studies revealed that taurine has a significant binding affinity with cyclin-dependent kinase 6 (CDK6), which is connected with cyclin partner and initiates a critical role in early phases of cancer development." (PMID 37834106, 2023). "Using The Cancer Genome Atlas TCGA and GTEx data analyze the expression and survival of CDK6 in patients in pan‐cancer, and cellular experiments were performed to verify the effect of CDK6 on cell function." (PMID 36457244, 2023). "In vivo experiment demonstrated the function of cdk6 in maintaining ABCB1-mediated drug resistance in cancers." (PMID 35459184, 2022). "In IOT, the LINC00324/miR-214-5p/CDK6|CCND1|MDM2|MDM4 axis promotes cancer cell proliferation and inhibits cancer cell apoptosis." (PMID 36620587, 2022). "As the key driver of cell division and G1/S transition, expression of CDK6 is tightly controlled in cancer cells." (PMID 35530358, 2022). "With the knockout of cdk6, quite a few of signaling factors leading to inhibition of cancer cell proliferation were found to be promoted." (PMID 35459184, 2022). "We concluded that targeting CDK6 by selonsertib can be an efficient therapeutic approach to cancer and other CDK6-related diseases." (PMID 35720007, 2022). "In this aspect, modernized functional biomaterials can be integrated for further enhancing the targeting inhibition on CDK6 in cancer cells." (PMID 35459184, 2022). "Evidence suggests that the alteration in the expression level of CDK6 involves cancer and is also found in neurodegenerative disorders like Parkinson’s." (PMID 35148332, 2022). "CDK6 is a key regulator in various cellular processes, such as cell proliferation, differentiation, inflammation, apoptosis and cancer, suggesting the importance of CDK6." (PMID 35148332, 2022). "All these reports highlight the importance of CDK6 as a potential therapeutic target to cure several pathological conditions, ranging from cancer to neurodegenerative disorders." (PMID 35148332, 2022). "At the pan-cancer level, the tumors with positive correlations between CDK6 expression and MSI are READ, KIRC, BRCA, SARC, CESC, LIHC, and OV and the tumors with negative correlations are THCA, UCEC, and PRAD." (PMID 35480115, 2022). "CDK4 and CDK6 are essential regulators of the initial phases of the cell cycle and are a promising anti-cancer treatment option." (PMID 35885460, 2022). "To observe the relationship between CDK6 expression and cancer progression, we compared the transcriptional level of CDK6 between MIBC (n = 62) and NMIBC (n = 103) in the GSE13507 cohort (including 165 BLCA cases)." (PMID 35463324, 2022). "On the other hand, such kind of inhibition induced by eL31 depletion led to the downregulation of cancer-associated elements P-Akt, CCND1, CDK6 and PIK3CA." (PMID 36309731, 2022). "As kinases, CDK4 and CDK6 play a crucial role in the G1-S phase transition, which is an important restriction point in the normal cell cycle, often reduced in cancer, leading to uncontrolled cell proliferation." (PMID 36505864, 2022). "Dysregulation of CDK6 activity affects various aspects of cancer cell proliferation, senescence, migration, apoptosis, and angiogenesis." (PMID 36046234, 2022). "WT mouse CRIPSCs also had higher expression of the genes related to stem cells (Psca, Atg9b, Sox2, Sox9), cell cycle (Cdk6), mammary luminal progenitor cells (Notch3 and Notch1), and cancers." (PMID 35841025, 2022). "Numerous studies have reported that miR-29s suppressed the proliferation and invasion of cancer cells by inhibiting the expression of CDK6 in different types of malignancies, including osteosarcoma, and gastric carcinoma, and bladder cancer." (PMID 36140219, 2022).